TLR4 (toll like receptor 4)
Diseases named in the same sentence as TLR4 in open-access papers (continued):
Sharing a sentence is not in itself a finding about the gene and the disease.
Obesity (continued). "Our findings support the paradigm that TLR4 represents a novel target for the treatment of insulin resistance and that TLR4 inhibitors could be useful therapeutics in the management of obesity-related metabolic disease." (PMID 26196892, 2015). "It was described that TLR2, TLR4, or TLR5 deficiency have a major role on obesity development." (PMID 26635627, 2015). "In obesity the TLR4 SNP rs4986790 was an independent predictor of SBP." (PMID 26435700, 2015). "TLR-4 activation by FFA or lipopolysaccharides (LPS) in adipocytes may be involved in the development of IR in obesity and DM2." (PMID 24673809, 2014). "TLR4 expression on macrophages, adipocytes and skeletal muscle cells is increased in obesity and essential for saturated fatty acid–induced activation of inflammation, meaning that potential activation of macrophage TLR4 by FFAs can be readily linked to insulin resistance." (PMID 24594974, 2014). "This crucial role of TLR4 has been confirmed by data demonstrating that deletions or mutations in TLR4 gene (MIM: 603030) protect against fatty acid-induced insulin resistance and diet-induced obesity." (PMID 24803744, 2014). "Besides, TLR4 also detects many endogenous molecules such as saturated fatty acid and induces sterile inflammation in a range of chronic diseases, including obesity and type 2 diabetes." (PMID 24347831, 2013). "Although it has been shown that Toll-like receptor 4 (TLR4) in the liver, muscle and adipose tissue plays an important role in obesity-associated inflammation and insulin resistance, the effect of TLR4 activation in the intestine has not been investigated." (PMID 24137239, 2013). "Blood levels of free fatty acids (FFA) are elevated in obesity and through their interaction with Toll-like receptor 4 (TLR4) FFA induce proinflammatory pathways in macrophages and other cell types that may promote insulin resistance." (PMID 23355833, 2013). "TLR4 appears to mediate the signal linking obesity to insulin resistance." (PMID 23741455, 2013). "In the present study, the high MNI ranking of Def6 in the subcutaneous adipose tissue of HFD-fed mice suggested that it might participate in the regulation of obesity-induced inflammation through TLR4 signaling." (PMID 23555558, 2013). "Recent investigations have shown that fatty acids do not activate TLR4 directly, questioning the real influence of this receptor in lipid-induced insulin resistance caused by obesity." (PMID 23840101, 2013). "In addition to the protection from ER stress, others and we observed that the deletion of the gene coding for TLR4 provides also a protection against obesity, probably because of a more favorable energy balance." (PMID 23741455, 2013). "The in vivo pathophysiological importance of TLR4 in obesity-induced inflammation and insulin resistance was investigated by using mice deficient in TLR4 signaling owing to invalidation of TLR4 (TLR4−/− mice) or to a loss-of-function mutation in the Tlr4 gene (C3H/HeJ and C57BL/10ScN)." (PMID 23316186, 2012). "Since TLR4 is a primary receptor mediating the proinflammatory effects of LPS, there seems to be a link between the bacteria-induced proinflammatory condition in the intestine to the development of diet-induced obesity." (PMID 23091640, 2012). "Since expression of receptors on cells is a key element in the regulation of proinflammatory cytokines, we determined whether TLRs (TLR2 and TLR4) and inflammatory cytokines expression was simultaneously modulated on PBMCs in obesity." (PMID 23191980, 2012). "In TLR4-deficient mice, this vascular proinflammatory gene cannot be expressed, regardless of the extent of obesity, dyslipidemia, or high fat intake." (PMID 23251812, 2012). "It has also been proposed that saturated free fatty acids, which are elevated in obesity, may generate insulin resistance through mechanisms that require activation of TLR4 and downstream pro-inflammatory signaling pathways." (PMID 22253759, 2012).
Obesity (continued). "TLR4 mediates vascular inflammation and insulin resistance in diet induced obesity." (PMID 22924123, 2012). "Moreover, genetic deletion designed to disrupt TLR4 signaling protects against high-fat diet-induced obesity." (PMID 22844271, 2012). "Emerging study proposed that TLR4 acts as a predominant molecular target for saturated fatty acids in the hypothalamus and triggers the intracellular signaling network that induces an inflammation response and that ultimately results to overeating and obesity." (PMID 22844271, 2012). "We found that loss of function mutation in TLR4 did not protect mice from high TF-diet-induced obesity, hyperglycemia, hyperinsulinemia, hypercholesterolemia, and hyperleptinemia." (PMID 21314942, 2011). "However, our findings in this model are at odds with the linkage of TLR4 and diet-induced obesity, hyperinsulinemia, and inflammation in response to diet high in saturated fat." (PMID 21314942, 2011). "In this present study, we investigated whether feeding TLR4 mutant mice a diet high in TF would offer protection against TF-induced obesity, insulin resistance, and inflammation in TLR4 mutant mice." (PMID 21314942, 2011). "Furthermore, TLR4 is associated with liver metastasis; researchers showed an increase in TLR4 expression in steatotic murine livers following diet-induced obesity." (PMID 22110526, 2011). "Moreover, TLR4 expression in adipocytes increases with obesity and it can be activated by LPS to induce NFκB activation and cytokine production in both rodent and human tissues." (PMID 20814545, 2010). "Studies in TLR4 mutant mice suggest that TLR signaling in the CNS may also contribute to obesity phenotypes by affecting nutrient intake." (PMID 20814545, 2010). "Similarly, free fatty acids binding innate immune receptors like Toll-like receptor (TLR4) have been shown to trigger significant inflammatory activities in the condition of obesity." (PMID 20508722, 2010). "The observations summed up above may indicate that the triad “adipocyte-macrophage-TLR4” might be involved in the inflammatory process occurring in obesity." (PMID 18350123, 2008). "LPS treatment activates the TLR4/NFκB signaling pathway, leading to the upregulation of pro-inflammatory genes such as IL-6 and VCAM-1, which are key mediators of vascular inflammation and endothelial dysfunction commonly associated with obesity and cardiovascular disease." (PMID 41010478, 2025). "In the state of obesity, massive expansion of adipose tissue, hypertrophy of white adipocytes, and macrophage infiltration in adipose tissue activates the complex of Toll-like Receptor 4 (TLR4) with LPS, which induces the production of pro-inflammatory adipocytokines, ultimately leading to IR." (PMID 41404514, 2025). "This suggests that ECT may modulate simple obesity through the TLR4/MyD88/NF‐κB signaling pathway." (PMID 40772014, 2025). "In addition, TLR4 deficiency in pro-opiomelanocortin (POMC) neurons can promote heat production and maintain a balance of lipid metabolism, but this ability only exists in male mice, which in turn increases the induction of obesity in female mice." (PMID 38275739, 2024). "Endotoxins such as LPS intensify the damage of gut barrier proteins (such as ZO1) and induce TLR4 signaling 24, consequently promoting the production of pro-inflammatory cytokines (such as IL1β), which exacerbate systemic low-grade inflammation and accelerate obesity pathogenesis 26–28." (PMID 38956395, 2024). "The binding of LPS to TLR4 can activate a wide array of cellular signaling pathways, inducing inflammation responses and the expression and secretion of cytokines within adipocytes and macrophages, leading to insulin resistance development and increased obesity." (PMID 38375360, 2024). "Additionally, SPV protected mice from obesity by inhibiting Cer synthesis and suppressing signaling in the TLR4/NF-κB pathway, and this process may have some relevance to insulin resistance." (PMID 38999906, 2024).
Obesity (continued). "Therefore, TLR4 might provide a new therapeutic target for the prevention and treatment of metabolic syndrome, including obesity and diabetes." (PMID 38275739, 2024). "Thus, reduced TLR-2 or TLR-4 signalling proteins could protect them from obesity and obesity-related IR." (PMID 37036026, 2023). "Accordingly high cholesterol and HFD would lead to low-grade pulmonary inflammation through activating TLR4/NFκB signaling while significant lower methylation of CpGs in the first exon of the TLR4 were observed in obese individuals, indicating epigenetic regulation of TLR4 expression in obesity." (PMID 36979493, 2023). "In addition, obesity, indicated by body mass index (BMI) over 30, interferes with the immune system including the activation of macrophages via toll-like receptors 4 (TLR4), which stimulates nuclear factor kappa B (NFĸB) signaling und further fuels inflammation of adipose tissue." (PMID 36710348, 2023). "TLR4 is expressed by adipocytes, and its activation leads to the production of proinflammatory cytokines and an intense immune response, both of which may play a role in the etiology of obesity." (PMID 36674680, 2023). "Thus, acupuncture may affect the regulation of obesity by inhibiting the activation of TLR4 via HMGB1 and thus downregulating NF-κB/IL-6 pathway." (PMID 36105933, 2022). "Moreover, ER stress could mediate inflammation via TLR4 signaling during the development of obesity." (PMID 36188456, 2022). "Therefore, LPS and SFA could act together to induce TLR4 dimerization and activation and thus, promote inflammation in obesity." (PMID 34960024, 2021). "Here, we demonstrate that the knockdown of TLR4-interactor with leucine-rich repeats (Tril), a functional component of TLR4, resulted in reduced hypothalamic inflammation, increased whole-body energy expenditure, improved the systemic glucose tolerance and protection from diet-induced obesity." (PMID 34504172, 2021). "However, female mice lacking TLR4 display higher risk of developing obesity, but also greater protection to insulin resistance, perhaps due to the lack of TLR4 signaling in important organs for metabolic homeostasis." (PMID 32903730, 2020). "Thus, elevated plasma FFAs in obesity have the potential to activate TLR4." (PMID 32403975, 2020). "Further studies are warranted to understand whether there is an association between miR-146a and miR-155 in regulating NF-kB and TLR4 signaling mediated inflammation, macrophage accumulation and insulin resistance in adipose tissue in long term obesity condition." (PMID 31477775, 2019). "However, macrophage-specific TLR4-deficient mice are not protected from obesity or insulin resistance induced by a HFD." (PMID 31582899, 2019). "Moreover, TLR4 known as a component of immune system Pattern-recognition receptors (PRRs), plays a crucial role as a trigger of metabolic inflammation and insulin resistance during obesity." (PMID 30906281, 2019). "In the context of obesity, the increase in the plasma fibrinogen levels, which represents a positive acute phase protein, acts as a factor that is involved in the activation of the TLR4 pathway, and, consequently, in the amplification of the inflammatory response." (PMID 29601492, 2018). "TLR4 knockout or antagonists may be beneficial for obesity-related asthma." (PMID 30050954, 2018). "The innate immune response initiates through the binding of LPS to Toll-like receptor 4(TLR4), which will induce the release of inflammatory cytokines, resulting in systemic inflammation and insulin resistance, similar to diet-induced obesity in animals and humans." (PMID 29434676, 2018). "Interestingly, TLR4 binds to and is activated by saturated fatty acids, which are abundant in obesogenic diets and may contribute to obesity-induced increases in inflammation and impaired insulin signaling." (PMID 30396359, 2018).
Obesity (continued). "Moreover, resveratrol and curcumin might inhibit obesity-related metainflammatory signals driven by toll-like receptor 4 (TLR4) and nucleotide-binding oligomerization domain 2 (NOD2)." (PMID 30134638, 2018). "In this study, we investigate whether down-regulation of TLR4 expression in hypothalamic ARC by stereotaxic injection of TLR4 shRNA lentiviral particles can improve the metabolic disorders in high-fat diet-induced obesity rat model." (PMID 28785099, 2017). "However, it is not clear whether SFAs engage similar transduction processes involving TLR4 and activating innate immunity in obesity-related cardiac injury." (PMID 28045026, 2017). "Our findings confirm the previous opinions that the TLR4 signaling pathway in hypothalamus is an attractive target for treatment of obese conditions, and further suggest that ARC-restricted TLR4 knockdown is a potential strategy to combat metabolic disorders associated with obesity." (PMID 28785099, 2017). "Therefore, the purpose of this study was to investigate whether the activation of TLR4 in the adipose tissues in a ligand independent and adipose‐specific manner induces metabolic changes, such as obesity and insulin resistance." (PMID 28776958, 2017). "Obesity is associated with low-grade inflammation, triggered in adipose tissue, which may occur due to an excess of SFA from the diet that can be recognised by Toll-like receptor-4." (PMID 29152245, 2017). "Recent studies have shown that increased levels of proinflammatory cytokines, including MCP-1, are involved in obesity and insulin resistance and that excess intake and endogenous release (lipolysis) of saturated fatty acids might enhance expression of TLR-4 target genes including MCP-1." (PMID 27881903, 2016). "However, it remains unknown whether there is a functional interaction between the role of TLR4 in diet-induced obesity and in visceral pain." (PMID 27159520, 2016). "Moreover, functional TLR4 is required for the development of high-fat diet-induced obesity." (PMID 27159520, 2016). "Importantly, TLR4 expression is increased in ATMs during obesity." (PMID 26779183, 2015). "Metformin and phosphatidylcholine attenuated lipopolysaccharide induced toll-like receptor 4 overexpression and overproduction of pro-inflammatory cytokines; however, their efficacy depended on combined presence of non-alcoholic fatty liver disease, metabolic syndrome and obesity." (PMID 26629827, 2015). "Therefore we investigated whether cases with a TLR4 SNP rs4986790 had ameliorated blood pressure in obesity as compared to controls." (PMID 26435700, 2015). "In addition to lipopolysaccharides from gram-negative bacteria, TLR4 can be activated by saturated free fatty acids during hyperlipidemic state associated with obesity and secondary to long-term ingestion of a high-fat diet (HFD)." (PMID 26539824, 2015). "Indeed, particular TLRs such as TLR2 and TLR4 link inflammation to metabolism and obesity." (PMID 25689154, 2015). "However, whether hyperinsulinemia can down-regulate the activation of TLR4 during obesity-related diseases require further investigation." (PMID 25101057, 2014). "Determination of whether TLR4 signaling can be activated in the heart by insulin may shed light on the pathogenesis of diabetic cardiomyopathy, a process that is often complicated by obesity and insulin resistance." (PMID 25101057, 2014). "Indeed, exposing macrophages and adipocytes to varying concentrations of palmitate, the most abundant circulating SFA in obesity, elicits a TLR4 dependent pro-inflammatory response characterized by increased NF-κB and JNK activation with resultant enhanced TNF-α cytokine secretion in vitro." (PMID 23675368, 2013). "Indeed, in addition to endotoxin, TLR4 may be activated by endogenous ligands that are increased in diet induced obesity and insulin resistance." (PMID 22709547, 2012). "TLR4 also may be activated by endogenous ligands that are increased in diet induced obesity and IR." (PMID 22709547, 2012).
Obesity (continued). "Similarly, nutritional fatty acids, whose circulating levels are often increased in obesity, activate TLR4 signaling in adipocytes and macrophages and the capacity of dietary fatty acids to induce inflammatory signaling in adipose cells or tissue and macrophages is blunted in the absence of TLR4." (PMID 22577589, 2012). "Furthermore, our results indicate that TLR4 independent pathways may be involved in TF-diet-induced obesity, hyperglycemia, hyperinsulinemia, and hyperleptinemia." (PMID 21314942, 2011). "It is not known whether loss of TLR4 function offers protection against trans fat (TF) induced obesity, inflammation, and insulin resistance." (PMID 21314942, 2011). "Thus, TLR4 activation contributes to the obesity inflammatory process." (PMID 20148136, 2010). "Thus the duo “saturated fatty acids plus TLR4” might be responsible for the amplification of inflammation occurring in obesity." (PMID 18350123, 2008). "DPR suppressed the expression of TLR4 and TLR9, key receptors that recognize mitochondrial DAMPs, further indicating that DPR limits obesity‐induced inflammaging signaling." (PMID 41549510, 2026). "Of note, relating to the identified potential miRNA interactions with TLR4, there is good evidence for involvement of hsa-miR-7-5p, hsa-miR-92a-3p, and hsa-miR-32-5p in GDM/obesity." (PMID 40910216, 2025). "In diseases such as obesity, a high frequency of haplotypes such as AGAC, GGAC, and AAAC has been observed, which correspond to SNPs of the TLR4 gene (A-2570G position 1, G-2081A position 2, A896G position 3, and C1196T position 4)." (PMID 40552316, 2025). "In obesity and T2DM, RBP4 is elevated in adipose tissue, contributing to systemic insulin resistance and inflammation through Toll-like receptor-4 (TLR4)." (PMID 40951890, 2025). "They found that consuming EGCG improves obesity, IR, NASH, liver injury, endotoxin‐TLR4‐NFκB inflammation, gut barrier dysfunction, and intestinal inflammation." (PMID 39139973, 2024). "In patients with obesity with T2DM, liraglutide exerted anti-inflammatory effect by lessening TLR4, NF-κB and downregulating the expression of proinflammatory factors including TNF-α." (PMID 39133777, 2024). "Mice genetically engineered to lack Toll-like receptor 4 (TLR4), which detects LPS, demonstrate resistance to diet-induced obesity and insulin resistance." (PMID 38474087, 2024). "Together, these data suggest that a link exists between PBMC TPR and human obesity and that TPR exerts pro-inflammatory effects in PBMCs via TLR4 and/or ROCK signaling." (PMID 39195211, 2024). "Obesity-induced inflammation (e.g., TNF-α, IL-1β and IFN-γ), as well as TLR4 protein expression and endotoxemia status, was also reduced after 12-week supplementation with L. acidophilus through NF-κB inhibition." (PMID 39421246, 2024). "Specifically, obesity leads to increased intestinal permeability and lipids, while elevated levels of circulating gut bacteria and free fatty acids may promote pro-inflammatory macrophage infiltration by binding to pattern recognition receptors such as TLR4 and TLR2." (PMID 39497804, 2024). "At the end of week 12, the final obesity modeling rates for male WT and TLR4−/− mice, and female WT and TLR4−/− mice, were 79%, 47%, 20%, and 43%, respectively." (PMID 38275739, 2024). "An example of this mechanism is how free fatty acids act as ligands for toll-like receptor 4 (TLR4), with TLR4-free mice in one study being protected from obesity induced by a diet rich in saturated fatty acids." (PMID 39125666, 2024). "Toll-like receptor 4 (TLR4) is a member of the pattern recognition receptor family and plays a role in the inflammatory process in animal models of obesity." (PMID 37732013, 2023). "Given that RSV is sensed by myeloid cells via TLR4/TLR8 pathways, we asked if maternal obesity compromises fetal myeloid cell responses to ex vivo RSV infection." (PMID 36645353, 2023).